TBX20 (T-box transcription factor 20)
Description:
Acts as a transcriptional activator and repressor required for cardiac development and may have key roles in the maintenance of functional and structural phenotypes in adult heart.
Synonyms: ASD4
Tractability: PROTAC: ubiquitination databases record sites on it.
Gene: Protein-coding gene on chromosome 7 (35,202,430 to 35,254,100, reverse strand). Ensembl gene ENSG00000164532.
Subcellular location: Nucleus
Subcellular location (Human Protein Atlas): Nucleoli fibrillar center
Pathways (Reactome):
Developmental Biology: Cardiogenesis
Gene Ontology:
Molecular function: DNA-binding transcription factor activity, RNA polymerase II-specific; RNA polymerase II transcription regulatory region sequence-specific DNA binding; sequence-specific double-stranded DNA binding; RNA polymerase II cis-regulatory region sequence-specific DNA binding; RNA polymerase II-specific DNA-binding transcription factor binding; DNA binding; DNA-binding transcription activator activity, RNA polymerase II-specific; DNA-binding transcription factor activity
Biological process: aortic valve morphogenesis; atrial septum morphogenesis; foramen ovale closure; outflow tract septum morphogenesis; pulmonary vein morphogenesis; atrioventricular canal development; atrioventricular valve development; cardiac chamber formation; cardiac muscle tissue morphogenesis; cardiac right ventricle morphogenesis; cardiac septum development; cell fate specification; dorsal/ventral pattern formation; embryonic heart tube morphogenesis; endocardial cushion formation; endocardial cushion morphogenesis; endoderm formation; heart looping; lateral mesoderm formation; mesenchymal cell development; negative regulation of DNA-templated transcription; negative regulation of transcription by RNA polymerase II; pericardium morphogenesis; positive regulation of BMP signaling pathway; positive regulation of cardiac muscle cell proliferation; and 14 more
Cellular component: chromatin; cytoplasm; nucleus
Genetic constraint (gnomAD): Loss-of-function variants: 8 observed, 38.17 expected, observed/expected ratio (o/e) 0.21, 90% interval 0.12 to 0.38. The upper end of that interval is the gene's LOEUF score, 0.38, which puts it in group 1 of 6, group 1 being the genes least tolerant of losing a copy. Missense variants: 404 observed, 564.19 expected, observed/expected ratio (o/e) 0.72, 90% interval 0.66 to 0.78. Synonymous variants: 192 observed, 221.28 expected, observed/expected ratio (o/e) 0.87, 90% interval 0.77 to 0.98.
Gene-disease validity (ClinGen):
ClinGen rates the evidence that TBX20 causes each of these diseases.
dilated cardiomyopathy (autosomal dominant): Strong. Cardiomyopathy which is characterized by dilation and contractile dysfunction of the left and right ventricles.
congenital heart disease (autosomal dominant): Moderate. A heart disease that is present at birth.
Homologues: Orthologues: chimpanzee TBX20 (100% identical), macaque TBX20 (99% identical), pig TBX20 (99% identical), dog TBX20 (98% identical), rat Tbx20 (98% identical), guinea pig TBX20 (98% identical), mouse Tbx20 (97% identical), rabbit TBX20 (90% identical), tropical clawed frog tbx20 (90% identical), zebrafish tbx20 (87% identical), Drosophila melanogaster mid (47% identical), Drosophila melanogaster H15 (47% identical), and 9 more. Paralogues in human: TBX15 (40% identical), TBX18 (40% identical), TBX22 (36% identical), TBX1 (33% identical), TBX2 (33% identical), TBX3 (32% identical), TBX5 (31% identical), MGA (30% identical), TBX4 (30% identical), TBX10 (30% identical), TBX6 (28% identical), TBR1 (25% identical), and 4 more.
Diseases named in the same sentence as TBX20 in open-access papers:
TBX20 is named in the same sentence as 57 diseases in open-access papers, as found by Europe PMC text mining. Sharing a sentence is not in itself a finding about the gene and the disease. The quoted sentences say what the papers report.
atrial septal defect (15 papers, 2014 to 2025). Interauricular communication is a congenital malformation characterized by a communication between the atrial chambers of the heart. "In humans, TBX20 gene variants have been associated with several congenital heart malformations, including atrial septal defect, double outlet right ventricle, tetralogy of Fallot, and ventricular septal defect (VSD)." (PMID 40760458, 2025). "Mutations in the coding region of TBX20 have been associated with sporadic and familial cases of coronary heart disease, including atrial septal defects (ASD), tetralogy of Fallot, and dilated cardiomyopathy in adults." (PMID 34204335, 2021). "Loss-of-function mutations in TBX20 can cause dilated cardiomyopathy, atrial septal defects, or mitral valve disease, while gain-of-function mutations in TBX20 have been reported in patients with tetralogy of Fallot." (PMID 33902696, 2021). "The ROC curve analysis indicated that methylation of the TBX20 gene could be considered a risk marker for congenital septal defects (AUC = 0.682; 95% CI = 0.58–0.77; p < 0.001)." (PMID 36831251, 2023). "In the present study, three patients harboring a TBX20 mutation (members II-8 and III-13 in Family 1 and member II-7 in Family 2) also had congenital atrial septal defects in addition to AF." (PMID 37759586, 2023). "Other potentially involved genes (GATA Binding Protein 4, GATA4; T-Box Transcription Factor 20, TBX20; NK2 Homeobox 5, NKX2-5; Zic Family Member 3, ZIC3) were initially recognized as pathogenic for Atrial Septal Defects (ASD)." (PMID 34946902, 2021). "A correlation analysis was conducted between DNA methylation levels of TBX20 gene promoter and age by study groups, and the result showed a moderate positive correlation in the septal defect group as well as in the PDA group (rho = 0.51 and 0.56, respectively; p < 0.0001)." (PMID 36831251, 2023). "Finally, TBX20 p.I122V was also studied as a change in the adjacent amino acid (TBX20 p.I121M), identified in a patient with an ostium secundum atrial septal defect, increased transactivation." (PMID 25093829, 2014). "Additionally, human Tbx20 mutations were associated with atrial septal defects and cardiomyopathy, whereas Tbx20 null mice die at mid-gestation due to the lack of proper heart chamber formation and cardiac hypoplasia." (PMID 27907103, 2016). "Several such mutations have been identified with developmental disorders such as atrial septal defect (ASD) associated with a mutation in GATA4 gene, and genes TBX5, TBX20 have been identified to result in ventricular septal defect (VSD) and left ventricular non-compaction (LVNC)." (PMID 35317745, 2022). "For example, in the case of atrial septal defect (ASD) and ventricular septal defect (VSD), candidate genes can be counted: NKX2-5, GATA4, TBX20, MYH6, and TBX5, while the pathogenesis of atrioventricular septal defect (AVSD) involves genes, such as PTPN11, KRAS, SOS1, RAF1, and CRELD1." (PMID 34946970, 2021).
cardiomyopathy (15 papers, 2015 to 2025). A disease of the heart muscle or myocardium proper. "It has been further demonstrated that ablation of Tbx20 in adult mouse cardiomyocytes leads to the onset of severe cardiomyopathy leading to death within 1–2 weeks after Tbx20 loss." (PMID 28945738, 2017). "Ablation of Tbx20 activity in adult cardiomyocytes disrupts the structure of myofibrils and causes arrhythmia in both Drosophila and mouse models, and mutations in tbx20 are associated with diverse cardiac pathologies including cardiomyopathy in humans." (PMID 27148546, 2016). "In adult mice, heterozygous loss of TBX20 leads to dilated cardiomyopathy and the conditional homozygous loss of TBX20 in cardiomyocytes results in severe cardiomyopathy with associated arrhythmias and death." (PMID 25834824, 2015). "Numerous variants of TBX20 have been reported to be associated with various CHDs, including hypoplastic right heart syndrome, a type of single ventricular morphology, as well as cardiomyopathy." (PMID 37180804, 2023). "Finally, we note that TBX20 is not only involved in CHD but is also associated with cardiomyopathy in patients." (PMID 37756602, 2023). "Mutations in human TBX20 that result in gain or loss of protein function are associated with a wide array of cardiac malformations, including septal defects, defects in valvulogenesis, and cardiomyopathy." (PMID 25834824, 2015). "To decipher the role of increased Tbx20 during ER stress–induced cardiomyopathy, we looked into the expression profile of proliferative (Ki67) and apoptotic markers (Chop and Bax) post ER stress induction in H9c2 cells." (PMID 36805334, 2023). "The study also showed that Bmp2 acts downstream of Tbx20 in imparting protection against ER stress–induced cardiomyopathy." (PMID 36805334, 2023). "In mice, ablation of Tbx20 in adult cardiomyocytes leads to severe cardiomyopathy and premature death." (PMID 37756602, 2023). "When the expression of Tbx20 is decreased during prolonged ER stress (2 days), the cardiac function is impaired resulting in progression of cardiomyopathy because of ER stress." (PMID 36805334, 2023). "In the current study, we examine the function of Tbx20 and bone morphogenetic protein 2 (Bmp2) signaling during ER stress–induced cardiomyopathy." (PMID 36805334, 2023). "In conclusion, it is inferred from our study that Tbx20–Bmp2 signaling acts during ER stress–mediated cardiomyopathy by increasing cardiomyocyte proliferation and limiting cardiomyocyte apoptosis." (PMID 36805334, 2023). "Next, we looked in the mode of action of Tbx20 in imparting protection against ER stress–induced cardiomyopathy." (PMID 36805334, 2023). "Ablation of Tbx20 in adult cardiomyocytes leads to severe cardiomyopathy with arrhythmias and death." (PMID 36805334, 2023). "Consistently inducible CM-specific Tbx20 KO in adult mice resulted in the onset of severe cardiomyopathy accompanied by arrhythmias and death within 1–2 weeks of Tbx20 ablation." (PMID 35898398, 2022). "Cardiac-specific Tbx20 KO in adult mice resulted in the onset of severe cardiomyopathy accompanied by arrhythmias, with death ensuing within 1 to 2 weeks of Tbx20 ablation." (PMID 34299340, 2021). "In mouse, cardiomyocyte-specific deletion of Tbx20 in adults leads to lethal cardiomyopathy and arrhythmia, indicating that TBX20 is required not only for cardiac development, but also for homeostasis." (PMID 30427827, 2018). "Cardiomyocyte-specific ablation of Tbx20 in adult mice leads to cardiomyopathies accompanied by arrhythmias, heart failure and ultimately death." (PMID 27907103, 2016). "Thus, studies on induction of cardiogenic gene Tbx20 or upregulation of the Tbx20–Bmp2–pSmad1/5/8 pathway in adult cardiomyocytes can protect them from ER stress–mediated cardiomyopathy and promote their regeneration." (PMID 36805334, 2023).
cardiomyopathy (continued). "Hence, these data suggest that Tbx20 directly binds to and induces the expression of atf6 during ER stress–mediated cardiomyopathy, thus maintaining the pool of atf6 during stressed conditions." (PMID 36805334, 2023). "The balance between ER stress–mediated cardiomyocyte survival and ER stress–mediated cardiomyocyte apoptosis is a critical factor that directs the protective effect of Tbx20, and it must be taken into account while considering therapeutic approaches to ER stress–mediated cardiomyopathies." (PMID 36805334, 2023). "Tbx20 overexpression was previously shown to induce proliferation of cardiomyocytes during oxidative stress and hypoxia; however, its mechanistic role during ER stress–mediated cardiomyopathy is still elusive." (PMID 36805334, 2023). "Next, we examined whether Tbx20 imparts its protective function during ER stress–mediated cardiomyopathy in rats also." (PMID 36805334, 2023). "Therefore, prolonging or maintaining the expression of Tbx20 for longer duration during ER stress could result in restoration of normal cardiac functions even during prolonged ER stress–mediated cardiomyopathy." (PMID 36805334, 2023). "In addition, we identify tbx20 as a direct target of Atf6 during ER stress–mediated cardiomyopathy." (PMID 36805334, 2023). "We identified further genes that regulate the development of trabeculation (NKX2-5, TBX20, HAND2, NRG1, NOTCH1 and DTNA) and those with evidence of involvement in cardiomyopathies (CRYAB and RIT1 (ARHGEF2))." (PMID 39567769, 2024). "The role of Tbx20 and Bmp2 signaling during ER stress–mediated cardiomyopathy has not been reported to date." (PMID 36805334, 2023). "However, the function and regulatory interactions of Tbx20 in ER stress–induced cardiomyopathy have not yet been reported." (PMID 36805334, 2023). "Cardiomyopathy can also occur with or without left ventricular dysfunction, as in left ventricular non-compaction cardiomyopathy (LVNC), which is a rare heart disease occurring due to two (likely) pathogenic nonsense mutations: DSG2-p.S363X and TBX20-p.D278X." (PMID 36475220, 2022).
congenital heart disease (15 papers, 2012 to 2025). "TBX20 has been mainly associated with congenital heart diseases and heart development, and mutations in TBX20 have also been found in patients with dilated cardiomyopathy." (PMID 35628236, 2022). "Since a number of studies have implicated mutations of the transcription factor TBX20 in congenital heart diseases, we investigated the underlying mechanisms, using an unbiased systems-based screen to identify novel, cardiac-specific binding partners." (PMID 28945738, 2017). "Pathogenic variants in TBX20 may impair its interaction with other cardiac transcription factors, potentially disrupting this regulatory network and contributing to congenital heart defects." (PMID 40760458, 2025). "Furthermore, mutations in TBX5 and TBX20 are associated with congenital heart disease in humans." (PMID 23533583, 2013). "TBX20, a cardiac TF regulated by TBX5, is essential for proper heart development with mutations that have been associated with congenital heart diseases." (PMID 37926287, 2023). "The TBX20 gene has a key role during cardiogenesis, and it has been related to epigenetic mechanisms in congenital heart disease (CHD)." (PMID 36831251, 2023). "Although mutations of NKX2-5, HAND1 and TBX20 have been found in patients with TOF, they are present only in a small percentage of patients with congenital heart disease." (PMID 22672592, 2012). "TBX20 is an ancient member of the TBX family which has been characterized to be essential for heart development and valvulogenesis in multiple animal models and mutations have been found in congenital heart disease probands." (PMID 35711915, 2022). "We would envision these findings are not restricted to TBX20 and CASZ1 but rather are applicable to other genes and other forms of congenital heart disease (CHD) and DCM, and predict that genome sequencing of familial CHD will ultimately reveal a spectrum of additional CHD susceptibility alleles." (PMID 28945738, 2017).
dilated cardiomyopathy (13 papers, 2013 to 2025). "Principle among these is how TBX20 mutations associated with adult dilated cardiomyopathy circumvent (DCM) the essential embryonic requirement for TBX20 in heart development." (PMID 28945738, 2017). "In addition, genetic variants of TBX20 have been found to be associated with dilated cardiomyopathy and heart arrhythmia." (PMID 33585493, 2021). "Vice versa, another research found overexpression of TBX20 in myocardium of TBX20 transgenic mice led to dilated cardiomyopathy that exhibited ventricular hypertrabeculation and an abnormal muscular septum." (PMID 38284443, 2024). "CASZ1 has been confirmed to interact with T-box transcription factor 20 (TBX20), and double haploinsufficiency of both genes induced dilated cardiomyopathy and cardiac fibrosis in mice." (PMID 37509718, 2023). "In the adult heart, Tbx20 haploinsufficiency gives rise to left ventricular dilation, and systolic and diastolic dysfunction, which resembles dilated cardiomyopathy (DCM) in humans." (PMID 33585493, 2021). "Tbx20 heterozygous mice survive postnatally but show dilated cardiomyopathy, which phenocopies at least a subset of human TBX20 mutant defects." (PMID 23936153, 2013). "Also variants in transcription factor genes, such as GATA4 and TBX20, have been associated with both CHD and dilated cardiomyopathy." (PMID 33194928, 2020). "In addition, TBX20 mutations have been discovered to contribute to dilated cardiomyopathy and/or left ventricular noncompaction, as well as atrial fibrillation." (PMID 40075846, 2025). "The common JAGs responsible for heart diseases included: JARID2 and TBX20, associated with a structural heart anomaly; JAZF1, associated with cardiac tumors; CAMK2G, associated with conduction defects; and CMAK2D and TMPO, associated with dilated cardiomyopathy." (PMID 29449671, 2018).
Arrhythmia (10 papers, 2015 to 2025). Any cardiac rhythm other than the normal sinus rhythm. "Studies by Shen and colleagues and Sakabe and coworkers showed that mice with conditional knockout of the Tbx20 gene in adult cardiomyocytes presented with cardiac expansion, a loss of contractile function, decreased heart conduction velocity, and severe arrhythmias." (PMID 37759586, 2023). "Mutations in TBX20 cause a complex and broad spectrum of heart defects, including septal defects, DCM, and arrhythmia." (PMID 34202524, 2021).
ventricular septal defect (10 papers, 2015 to 2025). The presence of a defect (opening) in the septum that separates the two ventricles of the heart. "This study aimed to investigate the potential role of TBX20 gene variants in the molecular pathogenesis of congenital ventricular septal defect (VSD) in pediatric patients." (PMID 40760458, 2025). "Furthermore, TFAP also interacts with Tbx20 resulting in the emergence of ventricular septal defects in patients with tetralogy of Fallot." (PMID 32413023, 2020). "The mutation of TBX20 gene may affect the regulation of downstream target gene ANF by TBX20 and other cardiac development related transcription factors, and further affect cardiac development, participating in the mechanism of CHD ventricular septal defect." (PMID 40760458, 2025).
Tetralogy of Fallot (9 papers, 2015 to 2023). A congenital cardiac malformation comprising pulmonary stenosis, overriding aorta, ventricular septum defect, and right ventricular hypertrophy. "TBX20 plays an important role in heart development; however, its epigenetic regulation in the pathogenesis of tetralogy of Fallot (TOF) remains unclear." (PMID 31138201, 2019). "Previous studies have evaluated the methylation status of the TBX20 gene in other types of CHD, specifically in tetralogy of Fallot (TOF)." (PMID 36831251, 2023). "Recently, hypomethylation of the TBX20 promoter region was observed in the tetralogy of Fallot patients, but no studies have been undertaken on VSD patients." (PMID 34204335, 2021).
heart failure (6 papers, 2016 to 2022). Inability of the heart to pump blood at an adequate rate to meet tissue metabolic requirements. "Published data has demonstrated a requirement for TBX20 in adult mice, with loss of TBX20 leading to abrupt cardiac failure." (PMID 28945738, 2017). "Out of the 42 murine cardiac fibroblast genes, 28 were present in both control and heart failure samples, including Tbx20, which was unchanged between control and heart failure." (PMID 35293863, 2022). "This affected many known genes and biological processes involved in DCM (e.g., TBX20, RBM20) or heart failure (NPPA, NPPB) and also revealed many novel DCM candidate genes." (PMID 28903782, 2017). "In contrast, we found that overexpressed Myc bound both the promoter region and body of many cardiac-specific genes including transcription factors (Gata4, Gata6, Tbx20, Nkx2-5), structural genes (Actc1, Pln), or heart failure related genes (Nppa, Nppb), but did not induce Pol II recruitment." (PMID 27346836, 2016).